EEF1A2 (eukaryotic translation elongation factor 1 alpha 2)
Diseases named in the same sentence as EEF1A2 in open-access papers (continued):
Sharing a sentence is not in itself a finding about the gene and the disease.
acute myeloid leukemia (2 papers, 2022 to 2024). Acute myeloid leukemia (AML) is a group of neoplasms arising from precursor cells committed to the myeloid cell-line differentiation. "They observed higher EEF1A2 mRNA and protein levels in acute myeloid leukemia (LAML) cell lines AML-193, Kasumi-1, and KG-1 compared with human normal bone marrow mononuclear cells." (PMID 38172654, 2024). "EEF1A2 overexpression promotes cell proliferation and inhibited apoptosis in acute myeloid leukemia." (PMID 35013140, 2022). "In the TCGA dataset of acute myeloid leukemia (LAML), there was a significant decrease in EEF1A2 expression, while no significant decrease was observed in EEF1A1 compared with normal GTEx samples." (PMID 38172654, 2024).
adenoma (2 papers, 2012 to 2022). A neoplasm arising from the epithelium. "Pilot evaluation in archive prostate tissues showed the presence of EEF1A2 mRNA in near all neoplastic and perineoplastic but not in normal samples or in benign adenoma; in contrast, EEF1A1 mRNA was everywhere detectable." (PMID 22095224, 2012). "Notably, in a fresh prostate benign adenoma sample, EEF1A1 but not EEF1A2 expression was detected, further stressing the concept that EEF1A2 switch-on occurs in neoplastic tissue." (PMID 22095224, 2012).
autosomal dominant non-syndromic intellectual disability (2 papers, 2020 to 2022). Autosomal dominant form of non-syndromic intellectual disability. "The human orthologue of Drosophila eEF1α2 gene is human eukaryotic translation elongation factor 1 α 2 (EEF1A2), which is associated with autosomal dominant non-syndromic intellectual disability and EIEE." (PMID 32899411, 2020).
colon adenocarcinoma (2 papers, 2022 to 2023). "Compared with tumor adjacent tissues, EEF1A2, PBK and TIMP1 showed significant upregulation in colon adenocarcinoma, while ATP2A3, CDC25C, MMP3 and NAT1 showed significant downregulation." (PMID 37626132, 2023).
colon cancer (2 papers, 2022 to 2023). "EEF1A2 served as an epithelial-mesenchymal transition-related gene that was found to be closely linked to the clinical outcomes of colon cancer, which was consistent with the outcomes of our study." (PMID 36518255, 2022).
Duchenne muscular dystrophy (2 papers, 2022 to 2024). Duchenne muscular dystrophy (DMD) is a neuromuscular disease characterized by rapidly progressive muscle weakness and wasting due to degeneration of skeletal, smooth and cardiac muscle. "Furthermore, in mdx mice, eef1a2 overexpression improves Duchenne muscular dystrophy, highlighting the relevance of this gene to tissue maintenance, formation, and morphology." (PMID 36553644, 2022). "This suggested that strategies focused on enhancing the expression and/or activity of eEF1A2 in muscles may offer therapeutic benefits for DMD (duchenne muscular dystrophy) patients." (PMID 38732031, 2024).
endometriosis (2 papers, 2018 to 2023). The growth of functional endometrial tissue in anatomic sites outside the uterine body. "It was reported that OCCC-associated endometriosis already harbors aberrant gene expression, such as altered expressions of eEF1A2, PTCH2, PPP1R14B, and XRCC5, which may not be found in endometriosis tissue in the absence of cancer." (PMID 29941051, 2018).
esophageal adenocarcinoma (2 papers, 2020 to 2024). A malignant tumor with glandular differentiation arising predominantly from Barrett mucosa in the lower third of the esophagus. "Among protein-coding genes, DriverPower identified EEF1A2 (eukaryotic translation elongation factor 1 alpha 2) in the oesophageal adenocarcinoma cohort (Eso-AdenoCA; 7/95 samples)." (PMID 32024818, 2020).
kidney cancer (2 papers, 2018 to 2020). Primary or metastatic malignant neoplasm involving the kidney. "Among the nine RBPs, EEF1A2, and RPL13 have been reported to be associated with tumorigenesis and progression of kidney cancer patients." (PMID 33133154, 2020). "Oncomine analysis of kidney cancer revealed that, EEF1A2 and EEF1B2 mRNA levels were upregulated in cancer samples." (PMID 29342219, 2018).
lymphoma (2 papers, 2010 to 2017). A malignant (clonal) proliferation of B- lymphocytes or T- lymphocytes which involves the lymph nodes, bone marrow and/or extranodal sites. "We screened 11 types of mouse lymphoma by microarray and found Eef1a2 as a candidate cancer gene that was expressed at high levels only in PCT." (PMID 20505761, 2010). "RT-PCR analyses of Eef1a2 expression in primary PCT, four other lymphoma subsets and normal spleen tissue showed that Eefla2 transcripts were detected only in samples from PCT (data not shown)." (PMID 20505761, 2010).
metastatic disease (2 papers, 2017 to 2018). "In metastatic tumor samples EEF1A2 overexpression was found in 52.6% of the patients." (PMID 28923030, 2017).
osteosarcoma (2 papers, 2024 to 2025). A usually aggressive malignant bone-forming mesenchymal neoplasm, predominantly affecting adolescents and young adults. "NSUN6 promoted osteosarcoma progression through EEF1A2 expression and inhibiting the AKT–mTOR signaling pathway via m5C methylation." (PMID 41462962, 2025). "Bioinformatics analysis and RIP and MeRIP assays identified and validated EEF1A2 as a potential target of NSUN6 in osteosarcoma." (PMID 41462962, 2025). "Reports state that DRD2 on the cell membrane can inhibit tumor growth by downregulating eEF1A2, whereas eEF1A2 increases osteosarcoma progression and degradation by triggering the Akt/mTOR signaling pathway, highlighting DRD2's anti-osteosarcoma effects." (PMID 38586328, 2024).
pheochromocytoma (2 papers, 2016 to 2023). "A study of pheochromocytoma cells also showed that stimulation with a nerve growth factor causes preferential synthesis of eEF1A1 over eEF1A2." (PMID 26981313, 2016).
Rett syndrome (2 papers, 2019 to 2023). A severe neurodevelopmental disorder affecting the central nervous system. "Using whole exome sequencing, we found a pathogenic variant in the EEF1A2 gene in a patient with a Rett syndrome-like (RTT-like) phenotype, further confirming the association between EEF1A2 and Rett syndrome RTT and RTT-like phenotypes." (PMID 31893083, 2019).
Atrophy (1 paper, 2013). Any weakening or degeneration, especially through lack of use. "Our study shows that loss of eEF1A2 leads to muscle atrophy resulting from loss of eEF1A2 in neurons." (PMID 24460877, 2013).
bovine tuberculosis (1 paper, 2024). "Several of the genes downregulated in Yakutian cattle were related to the susceptibility of a host to diseases, including Mycobacterium avium paratuberculosis, bovine tuberculosis, mastitis, brucellosis, and bovine respiratory disease (CD209, EEF1A2, SLC2A1)." (PMID 39333243, 2024).
brain tumors (1 paper, 2021). "A recent study has showed that eEF1A2, a subtype of eEF1A, can regulate expression and release of some cytokines in brain tumors, which implied EEF1A is associated with tumor immune microenvironment." (PMID 34446611, 2021).
cardiomyopathies (1 paper, 2021). "Of particular importance for this special issue is the fact that several de novo heterozygous missense mutations in the human EEF1A2 gene are associated with a subset of rare but severe neurological syndromes and cardiomyopathies." (PMID 34203525, 2021).
Cerebellar atrophy (1 paper, 2024). Cerebellar atrophy is defined as a cerebellum with initially normal structures, in a posterior fossa with normal size, which displays enlarged fissures (interfolial spaces) in comparison to the foliae secondary to loss of tissue. "In conclusion, Chp1 impacts on the biogenesis and also on the post-translational quality control of eEF1A F98C mutant derived from patients with EEF1A2-linked cortical/cerebellar atrophy." (PMID 38360885, 2024).
cervical squamous cell carcinoma (1 paper, 2024). A squamous cell carcinoma arising from the cervical epithelium. "Interestingly, the TCGA dataset pertaining to cervical squamous cell carcinoma and endocervical adenocarcinoma (CESC) revealed no significant change in the expression of EEF1A2 but a decrease in EEF1A1 expression compared with normal tissue and GTEx normal samples." (PMID 38172654, 2024).
developmental and epileptic encephalopathy, 33 (1 paper, 2022). Any early infantile epileptic encephalopathy in which the cause of the disease is a mutation in the EEF1A2 gene. "These clinical features are similar to BFNE caused by KCNQ2 variations and are different from those of autosomal-dominant nocturnal frontal lobe epilepsy (ADNFLE) caused by CHRNA4 variations and developmental and epileptic encephalopathy 33 (DEE33) caused by EEF1A2 variations." (PMID 35557555, 2022).
gastric ulcer (1 paper, 2022). An ulcerated lesion in the mucosal surface of the stomach. "Downregulation of Srm, Ryr-1, Eno3, Prkag3, and Eef1a2 genes involved in regulating arginine and proline metabolism, calcium signaling pathway, HIF-1 signaling pathway, oxytocin signaling pathway, and legionellosis are possibly involved in MD-4-mediated protection against gastric ulcers." (PMID 36292625, 2022).
hypopharyngeal squamous cell carcinoma (1 paper, 2018). "For tumors of head and neck type, Oncomine analysis revealed that mRNA levels of EEF1A2 and EEF1B2 were significantly lower in tongue squamous cell carcinoma, salivary gland adenoid cystic carcinoma and hypopharyngeal squamous cell carcinoma, respectively." (PMID 29342219, 2018).
kidney tumor (1 paper, 2020). "However, the antibody staining level of EEF1A2 and RPL36A were decreased from normal tissue to kidney tumor tissue." (PMID 33133154, 2020).
large cell lung carcinoma (1 paper, 2018). "Like EEF1A2, EEF1E1 transcript levels were also consistently elevated in small cell lung carcinoma, lung carcinoid tumor and squamous cell lung carcinoma subtypes as per Bhattacharjee’s study and, in large cell lung carcinoma, according to Hou’s dataset." (PMID 29342219, 2018).
lobular carcinomas (1 paper, 2005). "None of the three lobular carcinomas on the slide showed any eEF1A2 overexpression." (PMID 16156888, 2005).
lung carcinoid tumor (1 paper, 2018). A neuroendocrine neoplasm that arises from the lung. "Furthermore, EEF1A2 was significantly upregulated in lung carcinoid tumor, small cell lung carcinoma and squamous cell lung carcinoma subtypes, in Bhattacharjee’s dataset." (PMID 29342219, 2018).
malignant glioma (1 paper, 2018). A grade III or grade IV glioma arising from the central nervous system. "As per Pomeroy’s datasets, EEF1A2 displayed very high downregulation in malignant glioma, classic medulloblastoma, and in desmoplastic medulloblastoma." (PMID 29342219, 2018).
ovarian clear cell adenocarcinoma (1 paper, 2018). A malignant glandular epithelial neoplasm characterized by the presence of clear and hobnail cells. "While EEF1A1 was found to be downregulated in ovarian serous surface papillary carcinoma in Welsh’s dataset, EEF1A2 was upregulated in ovarian clear cell adenocarcinoma in Hendrix’s dataset." (PMID 29342219, 2018).
ovarian clear cell cancer (1 paper, 2007). An invasive malignant neoplasm that arises from the ovary and is characterized by a predominance of clear and hobnail malignant epithelial cells. "We have shown that, depending on the detection method used, up to 75% of ovarian clear cell carcinomas show overexpression of eEF1A2 at the protein level." (PMID 17437010, 2007).
prostate adenocarcinoma (1 paper, 2012). "The expression of EEF1A2 and EEF1A1 genes were analysed in four Finefix-fixed paraffin-embedded samples referred to four patients with a clinical diagnosis of prostate adenocarcinoma." (PMID 22095224, 2012).
rectal tumor (1 paper, 2020). "Conversely, it downregulated EEF1A2 in normal rectum organoids, PDE10A in normal colon organoids, and TGFB1 in rectal tumor organoids." (PMID 32824266, 2020).
renal cell carcinoma (1 paper, 2024). "Interestingly, high expressions of Myo18b, Ckmt2, and Eef1a2 showed unfavorable prognoses in H&N cancer, and Sln (sarcolipin) and Tceal7 are unfavorable for renal cell carcinoma." (PMID 38686626, 2024).
cancer (172 papers, 1994 to 2026). A tumor composed of atypical neoplastic, often pleomorphic cells that invade other tissues. "Although further research is required to conclusively establish EEF1A2 as a biomarker, its potential is promising, as multiple studies have demonstrated its association with cancer prognosis." (PMID 38172654, 2024). "Overexpression of EEF1A2 in cancer tissues is associated with poor prognosis and short survival of patients with LUAD." (PMID 33473168, 2021). "EEF1A2 is a protein translation factor that has been implicated in tumorigenesis in several cancers where it enhances cell growth and inhibits apoptosis." (PMID 32640573, 2020). "The expression of EEF1A2 in tissues other than specialised tissues has been associated to cancer development and aggressiveness, playing a role in ovarian, breast, lung, gastric, hepatic and pancreatic cancers." (PMID 22095224, 2012). "The progress in understanding the specific mechanisms and pathways associated with EEF1A2 in different cancer types, coupled with the availability of targeted therapies such as plitidepsin, provides hope for more effective and precise cancer treatments in the future." (PMID 38172654, 2024). "Notably, the proteins which had the biggest fold change in differentiated hVM1 clone 32 cells, GAP43, DCLK1, and EEF1A2, are implicated in several cancers." (PMID 35126116, 2021). "Recently, the EEF1A2-encoded eukaryotic elongation factor 1 alpha 2 (eEF1A2), which is a translation elongation factor with additional moonlighting functions, was reported to be overexpressed in many cancers and to promote tumor cell survival." (PMID 32824266, 2020). "Besides its role in cancer, EEF1A2 mutations are associated with characteristic facial features, intellectual disability, autistic behavior and epilepsy." (PMID 28923030, 2017). "The differential ability of the eEF1A isoforms to interact with signaling molecules discovered in this study could be associated with cancer-related properties of eEF1A2." (PMID 18221514, 2008). "The decision to target one or both of the EEF1A isoforms should be taken after consideration of the role of degree of pro-oncogenic role played by them in the specific tissue type, since we also see that EEF1A2 could be associated with a better survival rate in certain cancers." (PMID 38172654, 2024). "The structural peculiarities which underlay the cancer specificity of eEF1A2 remain unknown." (PMID 18221514, 2008). "In CRC, KAT8-mediated eEF1A2 K408la improves translational efficiency and enhances cancer cell proliferation." (PMID 40994548, 2025). "In CRC, eukaryotic translation elongation factor 1 alpha 2 (eEF1A2) K408la improves GTPase activity in response to aa-tRNA stimulation, accelerating ribosomal translation elongation and promoting cancer cell proliferation." (PMID 40994548, 2025). "Therefore, targeting these differences holds significant promise in that selective eEF1A2 inhibition could treat the neurological disorders caused by EEF1A2 mutations while sparing normal tissues, whereas eEF1A1-specific compounds might address cancers with oxidative stress vulnerabilities." (PMID 40806463, 2025). "More precisely, we have compiled studies in seven types of cancers that have reported EEF1A2 overexpression." (PMID 38172654, 2024). "Further research and clinical studies are warranted to explore the full potential of eEF1A2 as a target for cancer therapy, and to develop innovative and personalized treatments to combat this devastating disease." (PMID 38172654, 2024). "In conclusion, targeting EEF1A2 holds significant promise as a therapeutic strategy for cancer treatment." (PMID 38172654, 2024). "Collectively, these studies provide substantial evidence supporting the role of EEF1A2 in cancer prognosis." (PMID 38172654, 2024). "The upregulation of EEF1A2 in various cancers such as ovarian, hepatocellular, breast, prostate, lung, and pancreatic, signifies its role in tumorigenesis." (PMID 38172654, 2024).
cancer (continued). "This review presents the journey of finding increased expression of EEF1A2 in multiple cancers, establishing molecular mechanism, and exploring it as a target for cancer therapy." (PMID 38172654, 2024). "Numerous studies have highlighted the correlation between EEF1A2 and cancer prognosis, suggesting its potential as a biomarker." (PMID 38172654, 2024). "Specific gene therapy targeting EEF1A2 using clustered regularly interspaced short palindromic repeats (CRISPR) or an anti-EEF1A2 peptide can be designed to target EEF1A2 interactions, which can hinder the tumorigenesis property of cancer." (PMID 38172654, 2024). "EEF1A2, a coding gene crucial for protein translation elongation, has been demonstrated to exhibit altered expression in numerous cancers, which actively participate in the initiation and progression of various cancer types during carcinogenesis." (PMID 38957390, 2024). "Given these strong indications, it is imperative to conduct large-scale and systematic studies to firmly establish EEF1A2 as a biomarker for various types of cancers." (PMID 38172654, 2024). "The widely reported misexpression and redundant role of eEF1A2 in protein translation make eEF1A2 a very promising candidate for targeted therapy in cancers." (PMID 38172654, 2024). "Overall, the research consistently demonstrates that EEF1A2 expression promotes enhanced cell proliferation across various cancer types, suggesting its potential as a protumorigenic factor with implications for therapeutic targeting." (PMID 38172654, 2024). "In this review, we aim to summarize the research findings from 1991 to 2023 on the role of EEF1A2 as an oncogene across a wide variety of cancers." (PMID 38172654, 2024). "As aberrant overexpression of EEF1A2 is an exclusive nature of cancerous cells, it presents itself as an attractive candidate for therapeutic intervention in cancers." (PMID 38172654, 2024). "To understand the effect of EEF1A2 on survival, we will be discussing the correlation of EEF1A2 levels with the survival rates of patients in different carcinomas." (PMID 38172654, 2024). "Ever since the multiple roles and widespread overexpression of EEF1A2 in carcinomas have been identified, efforts have been made to target it for anticancer therapy utilizing miRNAs, natural products, and drugs." (PMID 38172654, 2024). "The authors concluded that EEF1A2 expression was elevated in 30% of all tumor tissues and carcinoma cell lines analyzed." (PMID 38172654, 2024). "As one of these first-in-class eEF1A2 degraders, 27 was shown to degrade eEF1A2 in three cancer cells in a dose-dependent manner, thus holding promise for the treatment of eEF1A2-mediated carcinogenesis." (PMID 36982256, 2023). "In cancer research, eEF1A1 and eEF1A2 proteins have been proposed as possible hallmarks for cell transformation and tumour progression." (PMID 35456960, 2022). "In a different study, transfection with pcDNA3.1-p16/pcDNA3.1-vi5-hisA-eEF1A2 plasmids led to eEF1A2 down-regulation through the increase in tumour-suppressor p16 and in turn inhibited cancer cell growth." (PMID 35805007, 2022). "We previously observed that eEF1A2 is a potential prognostic factor for prostate adenocarcinomas and plays a role in the development and progression of cancer cells." (PMID 35456960, 2022). "eEF1A2, an isoform of eEF1A, functions as cancer protein via a variety of mechanisms, such as facilitating cell invasion and migration by up-regulating MMP-9 and stimulating AKT in pancreatic tumors." (PMID 35127825, 2021). "The elongation factors, including EEF1A2, were studied in different cancer types, in COAD being downregulated, literature presenting them as biomarkers and therapeutic drug targets." (PMID 34073426, 2021). "The eEF1A2 is a protein translation factor involved in protein synthesis and with important anti-apoptotic, migration and pro-metastasis functions on cancer development." (PMID 33432064, 2021).